NTF3 (neurotrophin 3)
Diseases named in the same sentence as NTF3 in open-access papers (continued):
Sharing a sentence is not in itself a finding about the gene and the disease.
diabetic neuropathy (3 papers, 2014 to 2024). A chronic, pathological complication associated with diabetes mellitus, where nerve damages are incurred due to diabetic microvascular injury involving small blood vessels that supply these nerves, resulting in peripheral and/or autonomic nerve dysfunction. "However, slight increases in the expression of Ntf3, a critical human gene associated with diabetic neuropathy, were observed in dams exposed to PG/VG compared to control mice." (PMID 38540381, 2024). "Great interest has been generated by the role of nerve growth factors in the pathogenesis of DAN: for instance, insulin-like growth factor-1 (IGF-1) and neurotrophin-3 (NT-3) have been demonstrated to reverse experimental diabetic neuropathy." (PMID 25520703, 2014).
glaucoma (3 papers, 2011 to 2023). Increased pressure in the eyeball due to obstruction of the outflow of aqueous humor. "In the future, further in vitro and in vivo studies are required to show that optineurin causes glaucoma via regulating Bdnf, Ntf3, Snap25, and Nef1." (PMID 22194658, 2011). "Brain-derived neurotrophic factor, neurotrophin-3, and neurotrophin-4 are less studied neurotrophins in the ocular surface, even though brain-derived neurotrophic factor is well characterized in glaucoma, retina, and neuroscience." (PMID 36430547, 2022). "In contrast to NGF, investigations into effects of brain-derived neurotrophic factor, neurotrophin-4 (bind TrkB), and neurotrophin-3 (bind to TrkC) on the ocular surface are sparse, certainly less than those on the retina and on glaucoma." (PMID 36430547, 2022). "In addition, the role of neurotransmitters such as glutamate, glycine, dopamine, serotonin, etc., and neurotrophins, such as the brain-derived neurotrophic factor (BDNF), neurotrophin-3 (NT3), and neurotrophin-4/5 (NT4/5) in glaucoma, has also been extensively investigated." (PMID 37305138, 2023).
Huntington disease (3 papers, 2013 to 2024). Huntington disease (HD) is a rare neurodegenerative disorder of the central nervous system characterized by unwanted choreatic movements, behavioral and psychiatric disturbances and dementia. "Ntf3 could restore synaptic plasticity in the striatum of a mouse model of Huntington’s disease." (PMID 32997292, 2021).
liver cancer (3 papers, 2020 to 2022). An epithelial or non-epithelial malignant neoplasm that arises from the liver. "By analyzing the GSE45436 and GSE55092 datasets in the GEO and TCGA databases respectively, we found that NTF3 expression in the adjacent cancer tissues was significantly higher than that in the liver cancer tissues." (PMID 36263167, 2022). "Through the chi-square test, we found that the expression level of NTF3 in liver cancer tissue was significantly lower than the peritumor tissue." (PMID 34938753, 2021). "In our study, we first used HCCDB database to analyze the difference in NTF3 expression between liver cancer tissues and normal tissues." (PMID 34938753, 2021). "Our results indicate that NTF3 is under-expressed in liver cancer, which is closely related to poor prognosis." (PMID 34938753, 2021). "Multivariate Cox regression analysis further revealed that low NTF3 expression was an important unfavorable factor affecting the prognosis of liver cancer patients." (PMID 34938753, 2021). "In addition, we further confirmed that NTF3 was relatively low expressed in liver cancer tissues through immunohistochemistry." (PMID 34938753, 2021). "In view of our limited understanding of the role of NTF3 in liver cancer, we aimed to analyze its biological function in HCC through a comprehensive analysis of open-access databases to reveal its related regulatory pathways and specific roles in tumor immunity." (PMID 34938753, 2021). "In this study, we firstly used HCCDB database to analyze the differential expression of NTF3 mRNA in liver cancer and normal tissues and further used databases to analyze the correlation between NTF3 expression and liver cancer prognosis and tumor immune infiltration." (PMID 34938753, 2021). "We found that NTF3 mRNA expression was significantly decreased in liver cancer tissues." (PMID 34938753, 2021).
liver cirrhosis (3 papers, 2020 to 2024). "The analysis of the nine genes, namely A2m, Akr7a3, Aqp7, Ca3, Cdc2a, Cdkn3, Cyp2c11, Ntf3, and Sds, revealed the association between NGHCs and chronic inflammatory liver conditions, including liver cirrhosis and fibrosis." (PMID 32560183, 2020). "For example, the number of clinical samples was insufficient (only 74 cases), which did not fully explain the effect of NTF3 on tumor staging, tumor size, liver cirrhosis, lymph node metastasis and other clinicopathological indicators." (PMID 36263167, 2022).
neuroblastoma (3 papers, 2019 to 2024). Neuroblastoma (NB) is the most common solid, extracranial childhood tumor. "When introduced as an expression vector into mouse N2a neuroblastoma cells, a tractable model of neurodifferentiation, Caps2.L1 significantly increased neuron branching and neurotrophin-3 (Ntf3) release, compared to Caps2.1 and controls." (PMID 38773348, 2024).
allergic disease (2 papers, 2009 to 2020). An immune response that occurs following re-exposure to an innocuous antigen, and that requires the presence of existing antibodies against that antigen. "Neurotrophin 3 (NT-3) is a member of the neurotrophin family, a group of related proteins that are known to regulate neuro-immune interactions in allergic diseases." (PMID 19386090, 2009). "Increased expression of neurotrophin-3 and neurotrophin-4 was previously reported in allergies by several papers, although they were not studied as extensively as NGF or BDNF." (PMID 32596360, 2020).
bipolar depression (2 papers, 2014 to 2018). "Meta-analysis of three studies showed neurotrophin-3 levels were not significantly different from healthy controls in bipolar depression." (PMID 30113291, 2018). "Moreover, serum neurotrophin-3, neurotrophin-4/5, and GDNF are also altered in bipolar disorder." (PMID 25202283, 2014).
brain tumor (2 papers, 2025). "Similarly, the specific activation of neurotrophic factors, receptors TrkB and TrkC by their ligands neurotrophin 3 (NT3) and brain-derived neurotrophic factor (BDNF) via Akt and ERK pathways, promotes the survival of brain tumour-initiating cells." (PMID 41301734, 2025).
breast tumor (2 papers, 2016 to 2024). "The decreased levels of NTF-3 in breast tumor tissue in the brain are associated with reduced metastatic growth." (PMID 39408891, 2024). "Breast tumors with upregulated NTF-3 expression, compared to breast tumors with lower NTF-3 levels, have a greater ability to metastasize to the brain, particularly to form a macro-metastasis." (PMID 39408891, 2024). "Another report indicated that miR-200c may target an NF-κB up-regulated TrkB/NTF3 autocrine signaling loop in breast tumors." (PMID 27529418, 2016).
Cerebral atrophy (2 papers, 2021 to 2024). Atrophy (wasting, decrease in size of cells or tissue) affecting the cerebrum. "When neuroprotective factors, such as nerve growth factor, brain-derived neurotrophic factor (BDNF), neurotrophin 3 (NT-3), and neurotrophin 4/5 (NT-4/5) are deficient in MS patients, the influx of PBMC cells to the CNS can make up for this, slowing the rate of cerebral atrophy." (PMID 39201606, 2024).
Cerebral ischemia (2 papers, 2017 to 2022). Restriction of arterial blood supply to the brain associated with insufficient oxygenation to support the metabolic requirements of the tissue. "Furthermore, NeuN and VEGF expression were higher in the transplanted group and stem cell therapy partially prevented BDNF and neurotrophin-3 over-expression induced by cerebral ischemia." (PMID 35879657, 2022).
cognitive decline (2 papers, 2024 to 2025). "One study supports the idea of decreased Ntf3 following alcohol exposure being involved in compensatory mechanisms of cognitive decline associated with AUD." (PMID 41153338, 2025). "In our study, Ntf3 levels were significantly decreased in brain, WAT, and skeletal muscle tissues, highlighting its importance and connection to possible inflammation and cognitive decline." (PMID 41153338, 2025).
COVID-19 (2 papers, 2023 to 2024). A disease caused by infection with severe acute respiratory syndrome coronavirus 2. "Among them, serum levels of IL-10RB, FGF-19, and CCL-2 positively contributed to both hospitalized and critical COVID-19 conditions (OR: 1.10~1.16), while the other 4 proteins conferred risk on critical COVID-19 only (OR: 1.07~1.16), including EIF4EBP1, IL-7, NTF3, and LIF." (PMID 38455043, 2024). "Less is known about connections between phenotypes of COVID-19 and the levels of FGF-19, EIF4EBP1, and Neurotrophin-3 (NTF3)." (PMID 38455043, 2024).
epileptic seizures (2 papers, 2023 to 2024). "Therefore, we investigate the expression profiles of neurotrophin-3 and growth-associated protein-43 in children with epileptic seizures, to determine their potential role in epileptic seizures pathogenesis and diagnosis." (PMID 35349008, 2023). "In contrast, Dsp knockdown increased the expression of the mature neuronal markers Calb1, Tdo2, and Ntf3, which are negatively regulated by strong neuronal activation, such as in the ECS and epileptic seizures." (PMID 39176381, 2024).
medulloblastoma (2 papers, 2014 to 2022). A malignant, invasive embryonal neoplasm arising from the cerebellum. "The NTF3/TrkC signal inhibits growth in medulloblastoma (MBL) 12,13." (PMID 36263167, 2022).
melanoma (2 papers, 2016 to 2020). A malignant, usually aggressive tumor composed of atypical, neoplastic melanocytes. "Other receptors such as TrkC, the putative receptor for neurotrophin-3 (NT-3), are also highly expressed on melanoma cells and suggest that neurotrophins may help recruit metastatic melanoma cells to the brain." (PMID 27598148, 2016).
neuropathy (2 papers, 2014). A disorder affecting the nervous system that manifests with pain, tingling, numbness, and/or muscle weakness. "To determine if Ntf3 overexpression could either prevent, or promote recovery from, this noise-induced synaptic loss and attenuation of cochlear responses, we exposed control and Ntf3 overexpressing mice to noise levels known to cause this type of neuropathy (8–16 kHz at 100 dB SPL for 2 hr)." (PMID 25329343, 2014).
peripheral nerve injuries (2 papers, 2014 to 2023). "After peripheral nerve injury, several neurotrophic factors, such as BDNF, GDNF, NGF, and neurotrophin-3, are synthesized and secreted by SCs to promote neuroregeneration." (PMID 37071193, 2023).
type 2 diabetes mellitus (2 papers, 2020 to 2021). A type of diabetes mellitus that is characterized by insulin resistance or desensitization and increased blood glucose levels. "FOS, IGF1R, IGF2, FOXO1, and NTF3 might target “TGF-β signaling pathway”, “the hedgehog signaling pathway”, “retinol metabolism”, or “type II diabetes mellitus” pathways respectively." (PMID 32694937, 2020). "Based on the ceRNA network, we also discovered that FOS, IGF1R, IGF2, FOXO1, and NTF3 might target the “TGF-β signaling pathway”, “the hedgehog signaling pathway”, “retinol metabolism”, or “type II diabetes mellitus” pathways respectively, thereby modulating the subsequent development of ICC." (PMID 32694937, 2020).
alcohol addiction (1 paper, 2025). "Nek3, Ntf3, Cux1, and Irf6 expression changes were shared across at least three tissues and may be potential biomarkers of alcohol addiction." (PMID 41153338, 2025).
alcohol dependence (1 paper, 2017). Physical and psychological dependence on alcohol. "However, evidence of the effects of Ntf3/TrkC on alcohol dependence is scarce." (PMID 28614398, 2017).
autism (1 paper, 2021). Persistent deficits in social interaction and communication and interaction as well as a markedly restricted repertoire of activity and interest as well as repetitive patterns of behavior. "Increased levels of 3-NT were associated with increased levels of neurotrophin-3 (NT-3) in the cerebella of individuals with ASD, with increased levels in additional brain regions varying between the two brains with autism." (PMID 32929662, 2021).
chorioamnionitis (1 paper, 2009). A morphologic finding indicating inflammation of the fetal sac membranes. "The present study aims to evaluate, for the first time, the expression of Neurotrophin-3 in the human placenta during normal pregnancy and in preeclampsia and chorioamnionitis." (PMID 21151544, 2009). "Neurotrophin-3 protein expression and tissue distribution was evaluated by immunohistochemistry in placenta samples from uncomplicated first trimester (n = 5) and term (n = 5) pregnancies as well as in specimens from preeclampsia (n = 5) and chorioamnionitis (n = 5)." (PMID 21151544, 2009).
deafness (1 paper, 2025). An inherited or acquired condition characterized by the complete loss of the ability to hear from one or both ears. "A possible downstream effect provides evidence for a pathophysiological mechanism of deafness and shows how genes involved in different forms of deafness may interact together, including Bdnf/Ntf3." (PMID 40823538, 2025).
insomnia (1 paper, 2024). A sleep disorder characterized by difficulty in falling asleep and/or remaining asleep. "Moreover, it is noteworthy that among genomic factors, only the expression of NTF4 and NTF3 genes in the healthy control group were predictive of insomnia severity and the onset of clinically significant disease, respectively." (PMID 39126038, 2024). "The neurobiological underpinnings of both OSA and insomnia involve complex interactions among various neuromodulators, including brain-derived neurotrophic factor (BDNF), its precursor proBDNF, glial-cell-line-derived neurotrophic factor (GDNF), neurotrophin-3 (NTF3), and neurotrophin-4 (NTF4)." (PMID 39126038, 2024). "However, it must be mentioned that individuals with no clinically significant insomnia had higher expression levels of BDNF and NTF3 in the OSA group compared to controls." (PMID 39126038, 2024).
interstitial lung disease (1 paper, 2024). A diverse group of lung diseases that affect the lung parenchyma. "However, in a study on eight individuals affected by respiratory bronchiolitis-associated interstitial lung disease, no changes in BDNF were revealed, but a faint expression of neurotrophin-3 and other neurotrophin receptors was detected." (PMID 39403060, 2024).
keloid (1 paper, 2025). An irregularly shaped, elevated mark on the skin caused by deposits of excessive amounts of collagen during wound healing. "External dataset validation, qPCR, correlation analysis, HE staining, and IHC results demonstrated that EDN1 and NTF3 were highly expressed in keloid tissues and were associated with excessive collagen deposition and immune cell infiltration." (PMID 40051702, 2025). "This study found that the abnormal overexpression of key genes, such as EDN1 and NTF3, in keloid tissues is closely associated with significant fibrotic and inflammatory phenotypes." (PMID 40051702, 2025). "The ROC analysis revealed that EDN1 and NTF3 exhibited high sensitivity and specificity in distinguishing keloid tissues from normal tissues, highlighting their potential value as biomarkers." (PMID 40051702, 2025). "As a result, EDN1 and NTF3 were identified as the most important hub genes, warranting further investigation into their roles in the formation and progression of keloids." (PMID 40051702, 2025). "The immune cell infiltration and correlation analysis in keloid tissues revealed significant associations between the expression of the hub genes ADRB2, NTF3, VCAM1, EDN1 and various immune cell types." (PMID 40051702, 2025). "Similarly, NTF3 exhibited stronger staining in the keloid dermis, particularly within the fibrotic regions." (PMID 40051702, 2025). "EDN1 and NTF3, as OSRDEGs, play critical roles in the pathogenesis and progression of keloids." (PMID 40051702, 2025). "Similarly, NTF3 also exhibits elevated expression in keloid tissues, whereas its expression in normal skin remains minimal." (PMID 40051702, 2025). "At the transcriptome-wide level, this further suggests that EDN1 and NTF3 may play dual regulatory roles in the fibrosis and inflammation processes of keloids." (PMID 40051702, 2025). "The heatmap illustrates the differential expression of these 13 OSRDEGs between keloid and normal skin tissues, where F3, FOXL2, EDN1, and NTF3 show higher expression in keloid tissues, while BDNF, FLT1, VCAM1 and ADRB2 are more highly expressed in normal skin." (PMID 40051702, 2025). "For instance, valproic acid is predicted to interact with NTF3, while dexamethasone is associated with VCAM1, suggesting that these genes could serve as potential therapeutic targets for modulating gene activity in the treatment of keloids." (PMID 40051702, 2025). "In the violin plot, EDN1, NTF3, ADRB2, and VCAM1 were found to be significantly upregulated in keloid tissue, with very high statistical significance (***, p < 0.001)." (PMID 40051702, 2025). "In keloid tissues, EDN1 and NTF3 were significantly upregulated, accompanied by prominent fibrotic features such as thickened and disorganized collagen fibers." (PMID 40051702, 2025). "Ultimately, 7 hub genes—EDN1, NTF3, VCAM1, ADRB2, BDNF, F3 and FLT1—were identified, all of which had interaction scores above 0.70, indicating their potential roles in keloid formation and progression." (PMID 40051702, 2025). "The qPCR analysis of NTF3 and EDN1 mRNA expression levels in normal skin and keloid tissue reveals a significant increase in both genes in keloid tissues." (PMID 40051702, 2025). "Additionally, EDN1 and NTF3 exhibited high correlations with fibrosis markers (COL1A1, TGFB1), inflammatory cytokines (IL6, TNFA), and immune cell infiltration (e.g., activated mast cells), suggesting their central regulatory roles in keloid-associated fibrosis and inflammation." (PMID 40051702, 2025). "In contrast, keloid tissues exhibited significantly higher expression levels of both EDN1 and NTF3." (PMID 40051702, 2025).
liver fibrosis (1 paper, 2025). "Previous work has demonstrated that targeting the neurotrophin-3/NTRK3 axis can suppress liver fibrosis by disrupting autocrine/paracrine HSC signaling." (PMID 40678531, 2025). "A recent study highlighted the critical role of autocrine signaling circuits involving neurotrophin 3 and its receptor in liver fibrosis." (PMID 40678531, 2025).
lung carcinoma (1 paper, 2024). "The expression of the NTF-3 has also been shown in lung squamous cell carcinoma tissue, but its role in the mechanism of lung carcinoma development is unclear." (PMID 39408891, 2024).
mood disorder (1 paper, 2024). A cognitive disorder a disturbance in which the person's mood is hypothesized to be the main underlying feature. "Hence, further research is warranted to explore the prognostic and diagnostic value of Neurotrophin-3 in MD, its role in pathogenesis, and the efficacy of Neurotrophin-3-targeted treatments, leveraging insights from previous studies on mood disorders and this MR study." (PMID 38742115, 2024). "While Neurotrophin-3 holds promise as a pharmacological target for mood disorders, its function in MD remains unclear." (PMID 38742115, 2024).
myeloma (1 paper, 2022). "In agreement with the gene model, compared with bortezomib-sensitive myeloma cell lines (negative control), there was an increase in mRNA expression of SCN9A, RGS7, NTF3, HSPB8, and ZBED1 and a decrease in CCND1, COBLL1, EGR1, OCLN, and ZBED1 mRNA expression of bortezomib-resistant cell lines." (PMID 36467498, 2022).